INS (insulin)
Diseases named in the same sentence as INS in open-access papers (continued):
Sharing a sentence is not in itself a finding about the gene and the disease.
Insulin resistance (continued). "Flavonoids, by acting as insulin sensitizers, improve insulin signalling and glucose metabolism, reducing insulin resistance and thereby preventing hyperinsulinemia-induced androgen production by the ovaries." (PMID 41370421, 2025). "Appropriate physical activity can additionally reduce serum insulin levels, regulate insulin receptors, improve carbohydrate utilization and insulin resistance (IR), and then normalize blood glucose levels." (PMID 40969632, 2025). "Hepatic iron overload, often exacerbated by viral co-infections such as hepatitis B and C, impairs insulin clearance and promotes insulin resistance." (PMID 40924301, 2025). "Insulin resistance, characterized by the reduced effectiveness of insulin in target organs, is regarded as the central mechanism underlying metabolic syndrome." (PMID 40800025, 2025). "One example is miR-26a, which is highly expressed in BAT and correlates negatively with body mass index, Homeostatic Model Assessment for Insulin Resistance, fasting glucose, and insulin levels in humans." (PMID 40658727, 2025). "This was the first study to examine the associations between maternal and cord serum lipidome and childhood insulin secretion and insulin resistance." (PMID 40544417, 2025). "The effect of luteolin on insulin sensitivity in this investigation was corroborated by recent research demonstrating that luteolin alleviated insulin resistance in metabolic-syndrome-induced cardiac injury rats." (PMID 40332475, 2025). "When various internal and external factors drive target cells toward insulin resistance, greater amounts of insulin are required to trigger glucose transport and utilization." (PMID 39995417, 2025). "The main pathomechanisms in which T2DM is developed are the defect of insulin production and insulin resistance (IR) in peripheral tissues." (PMID 39940862, 2025). "Under basal conditions, the most abundant subpopulation was P8 for both normal insulin sensitivity and advanced insulin resistance groups (94.6 ± 1.5 and 79.2 ± 1.7, respectively), showing that most platelets in the total population are quiescent." (PMID 40304758, 2025). "The 14-week randomized crossover study demonstrated that a high dose of strawberry powder significantly reduced fasting insulin (p = 0.0002) and insulin resistance (p = 0.0003)." (PMID 40218884, 2025). "Type 2 diabetes (T2D) is a chronic metabolic disorder characterized by insulin resistance, impaired insulin secretion, and systemic inflammation." (PMID 40562870, 2025). "Although normal aging is often accompanied by insulin resistance and decreased insulin secretion, short-term exercise has been found to not only improve insulin sensitivity but also enhance β-cell function in elderly IGT patients." (PMID 41357171, 2025). "Inhibition of prolyl hydroxylase (PHD) can also improve insulin resistance and lower serum insulin levels." (PMID 40000368, 2025). "Gingerol administration resulted in a significant reduction in body weight gain, glucose, and insulin levels, and insulin resistance." (PMID 40733199, 2025). "Overexpression of the anti-inflammatory cytokine IL-10 can protect adipocytes in insulin-sensitive tissues from TNF-α–induced insulin resistance, thereby controlling diabetes progression." (PMID 41357227, 2025). "Correspondingly, studies on fetuin-A knockout mice have demonstrated increased insulin sensitivity, whereas wild-type mice treated with exogenous fetuin-A exhibit acute insulin resistance." (PMID 41341358, 2025). "For example, prenatal treatment with excess T in sheep results in metabolic changes including disrupted insulin secretion dyslipidemia and peripheral insulin resistance in female offspring." (PMID 40914344, 2025). "Beyond hyperglycemia, insulin resistance and impaired insulin signaling also play a key role in endothelial dysfunction." (PMID 40429748, 2025).
Insulin resistance (continued). "Substantial S-nitrosylation of IR, IRS-1, and Akt has been observed in obese rodent models, inhibiting insulin signaling and promoting insulin resistance." (PMID 41226411, 2025). "Following dual agonist stimulation, the higher concentration of PGI2 (100 nmol/l) showed diminished inhibition in the advanced insulin resistance group compared with the normal insulin sensitivity group." (PMID 40304758, 2025). "A. muciniphila, the sole representative of Bacillariophyta (phylum of warts and microfungi), was identified to enhance insulin sensitivity and alleviate insulin resistance, thereby advancing its study in metabolic research." (PMID 40309112, 2025). "As abdominal obesity progresses, insulin resistance occurs, and insulin secretion increases due to the compensatory response of beta-cells." (PMID 40395818, 2025). "Several studies evaluated the effects of different NIADs on insulin sensitivity in healthy, obese cats, which serve as a natural model for insulin resistance." (PMID 40941356, 2025). "When there is chronic fuel overload due to overnutrition, insulin resistance is a physiological defense mechanism of the body protecting insulin-sensitive tissues from fuel overload and fuel toxicity." (PMID 41009753, 2025). "In terms of insulin, a unit increase demonstrated a 214% increase in the odds of having insulin resistance." (PMID 40802820, 2025). "To further assess insulin sensitivity, we calculated the homeostatic model assessment of insulin resistance (HOMA-IR), where higher values indicate greater insulin resistance." (PMID 40864772, 2025). "Body weight (Weight_Final) contributed the most, followed by homeostatic insulin resistance (HOMA_IR) and fasting plasma insulin levels (Insulin_Fasting)." (PMID 40595617, 2025). "In turn, insulin resistance exacerbates the condition by impairing insulin's antilipolytic effects, resulting in increased plasma FFAs." (PMID 40862144, 2025). "The ob/ob mice also exhibited systemic dysregulation of glucose metabolism, which was primarily manifested by elevated blood glucose and serum insulin levels, insulin resistance and impaired glucose tolerance." (PMID 40159625, 2025). "Through these pathways, PGC-1α enhances glucose uptake and regulates insulin action, ensuring proper glucose utilization and preventing insulin resistance." (PMID 40926269, 2025). "Studies have shown that exosomes derived from bone marrow macrophages (BMMs) can alleviate insulin resistance in hepatocytes and enhance insulin sensitivity through miR-143-5p and miR204/Elovl6." (PMID 41488105, 2025). "Previous researches have shown that insulin can prompt the proliferation of pancreatic cancer cells, and that insulin resistance accelerates the progression of pancreatic ductal carcinoma in animal studies." (PMID 40168281, 2025). "Disruption of JAZF1 in iPSCs derived from knockout mice leads to reduced size and impaired differentiation of insulin-producing β-cells, resulting in decreased insulin production and insulin resistance." (PMID 41227365, 2025). "Insulin resistance is defined as a diminished responsiveness of insulin-targeting tissues to elevated levels of this hormone." (PMID 40283443, 2025). "It was previously believed that because type 2 diabetes is a function of insulin resistance, there was still adequate insulin secretion from the pancreas to prevent ketone buildup." (PMID 40978981, 2025). "Together, these findings highlight a dual impact of IH on both ECM remodeling and insulin signaling, providing mechanistic insight into how IH contributes to adipose tissue dysfunction, abnormal metabolism and insulin resistance." (PMID 41409157, 2025). "BCAA has been proposed as a possible causal component in the insulin resistance (IR) etiology and T2DM by contributing to mitochondrial overload with lipid substrates, which leads to mitochondrial stress and decreased insulin action." (PMID 39791169, 2025).
Insulin resistance (continued). "Metformin is well-known for decreasing insulin resistance by enhancing insulin receptor signaling, reducing circulating insulin levels, and normalizing the LH/FSH ratio, thus promoting follicular development and ovulation." (PMID 41411269, 2025). "The physiological insulin resistance that develops during pregnancy is typically compensated by increased insulin secretion." (PMID 40145401, 2025). "This insulin resistance triggers a compensatory increase in insulin secretion, disrupting the insulin-like growth factor (IGF) system." (PMID 40430234, 2025). "Similar to insulin levels alterations, the NI+HF (17 ± 3.5) and NI+HF+GP (13 ± 2.1) groups displayed higher insulin resistance compared to the NI group (3.1 ± 0.16, p < 0.005, 0.01)." (PMID 40104317, 2025). "The inhibition of insulin signaling was demonstrated in mice by MG-53, which led to insulin resistance and metabolic syndrome." (PMID 40416219, 2025). "This accumulation of BCAAs and AAAs in plasma further exacerbates insulin resistance by interfering with insulin signaling pathways." (PMID 40362828, 2025). "A disturbance in the insulin-signaling pathway results in impaired insulin action and insulin resistance." (PMID 39859066, 2025). "Various mechanisms have been identified that explain how ceramides contribute to the development of insulin resistance, particularly at the receptor and post-receptor stages of insulin action." (PMID 40700071, 2025). "Kaempferol regulates insulin signaling pathways, ameliorates insulin resistance, and enhances glucose metabolism through interactions with NF-κB, SIRT1, and AMPK cascades." (PMID 40699849, 2025). "Hyperinsulinemia is likely a late consequence of insulin resistance—having abnormally high insulin levels in the bloodstream." (PMID 40362446, 2025). "Studies have found a positive correlation between sphingomyelin levels in adipocytes, insulin levels, and the insulin resistance index (HOMA-IR) in individuals with excess body weight." (PMID 39940917, 2025). "The Insulin Resistance (IR) explains the failure of muscles, fat, and liver to respond well to insulin and their incapacity to take up glucose from the blood." (PMID 40492113, 2025). "The HBOT seems to improve glycaemia levels and insulin sensitivity, thus making it a weapon worth investigating in the fight against insulin resistance and its consequences (e.g., metabolic syndrome and T2D)." (PMID 41322229, 2025). "In the present study, insulin suppressed canonical lipolysis; however, LPS exposure impaired insulin’s ability to inhibit lipolysis, indicating the development of insulin resistance." (PMID 40458405, 2025). "Its pathogenesis involves β-cell compensation to meet the increased insulin demand driven by insulin resistance." (PMID 41438030, 2025). "Type 2 diabetes is the most predominant form of diabetes, arising from the combination of insulin resistance and impaired insulin secretion due to the dysfunction of pancreatic β-cells." (PMID 40143139, 2025). "Ning proposed that the mechanism by which DHM reduces insulin resistance may involve the enhancement of antioxidant activity, which alleviates alloxan-induced damage to the liver and pancreatic beta cells, a process closely associated with hepatic glycogen synthesis and insulin production." (PMID 40740995, 2025). "Taken altogether, thyroid dysfunction can worsen insulin resistance by altering adipokine levels, with hypothyroid patients often having high leptin and low adiponectin, impairing liver insulin signaling and fat buildup." (PMID 41411310, 2025). "Insulin resistance is a condition characterized by a diminished sensitivity and response to insulin, leading to an impaired ability of insulin to facilitate glucose transport into cells." (PMID 39746074, 2025).
Insulin resistance (continued). "In T1D, this process occurs due to several mechanisms, including hepatic and peripheral insulin resistance, hyperglycaemia‐induced regulation of lipid metabolism, altered hepatic insulin delivery and lipoprotein abnormalities." (PMID 40654205, 2025). "A prospective cohort study further demonstrated that T2DM patients with elevated fasting insulin levels and higher homeostasis model assessment of insulin resistance (HOMA-IR) scores have a significantly increased incidence of OSA." (PMID 40909136, 2025). "By protecting islet cells, reducing insulin resistance, and ultimately enhancing glucose absorption, galactomannan promotes insulin production." (PMID 41509111, 2025). "Reduced hepatic insulin clearance, due to increased delivery of free fatty acids released from the adipose tissue to the liver, leads to hyperinsulinemia and insulin resistance." (PMID 40141439, 2025). "Notably, the magnitude of insulin sensitivity improvement may depend on the metabolic status of individuals, with pronounced benefits observed among those with underlying metabolic dysfunction and insulin resistance." (PMID 41228539, 2025). "Especially, overexpression or abnormal expression of SNAP-25 has been linked to insulin resistance, as SNAP-25 acts as a physiological brake to impair insulin action, while attenuation or deficiency of SNAP-25 results in higher insulin sensitivity." (PMID 40790236, 2025). "In T2DM insulin resistance (IR) is a key mechanism and is influenced by autophagy, which regulates β-cells and insulin-responsive tissues, such as the adipose tissue, liver, and skeletal muscle." (PMID 39859520, 2025). "The homeostasis model assessment of insulin resistance (HOMA-IR) was significantly reduced in the insulin group (p < 0.05), but remained unchanged in the GLP-1RA and control groups." (PMID 40496556, 2025). "Insulin resistance is a state of decreased responsiveness to high physiological insulin levels in physiologically insulin-targeting tissues." (PMID 40792244, 2025). "Clinical evidence shows that serum testosterone levels correlate positively with insulin sensitivity and negatively with insulin resistance." (PMID 41427055, 2025). "GIP-induced vasodilation is blunted in adipose tissue of people living with obesity and insulin resistance, and in healthy humans upon antagonism of GIPR, and normalizes upon weight loss and restoration of insulin sensitivity." (PMID 40024571, 2025). "Insulin resistance is defined as the impaired biological response of target tissues to insulin stimulation." (PMID 40729004, 2025). "Insulin resistance is commonly defined as the inability of insulin to transport glucose inside the cell, which eventually causes hyperinsulinemia and impaired glucose tolerance." (PMID 41465047, 2025). "Clinical and experimental studies have demonstrated that regular fasting cycles can decrease fasting insulin levels, reduce insulin resistance markers, and enhance the insulin-mediated glucose disposal rate." (PMID 40647240, 2025). "In CgA knockout mice, obesity and peripheral insulin resistance coexist with improved hepatic insulin sensitivity." (PMID 41480370, 2025). "Insulin resistance, the inability of a given amount of insulin to sufficiently stimulate glucose uptake and utilization, is a hallmark feature of type 2 diabetes." (PMID 40843663, 2025). "Chronic low-grade inflammation can interfere with insulin signalling, leading to insulin resistance and subsequently triggering T2DM." (PMID 40878475, 2025). "Any defect in this reassembly process can lead to reductions in IRV abundance or insulin sensitivity, thereby contributing to insulin resistance." (PMID 40806697, 2025). "A 2022 metanalysis found that Vitamin E supplementation reduced fasting glucose, fasting insulin, homeostasis model assessment of insulin resistance (HOMA-IR), total cholesterol, LDL-cholesterol, triglycerides, total testosterone, and increased SHBG." (PMID 40149685, 2025).
Insulin resistance (continued). "Under conditions of insulin resistance, impaired muscle insulin signaling disrupts skeletal muscle glucose uptake and metabolism, leading to hyperglycemia." (PMID 41551513, 2025). "Based on our results we recognize the value of incorporating metabolic data—such as body weight, caloric intake, and insulin levels—as well as brain insulin resistance markers (e.g., phospho-IRS, phospho-AKT, and phospho-GSK3β)." (PMID 40948809, 2025). "We also compared other indicators between baseline and 6 months posttreatment, including fasting insulin levels, insulin resistance indicators, hepatorenal biochemical parameters, and the prevalence of renal dysfunction and lipidemia disorder." (PMID 41261617, 2025). "The study found that L-carnitine uptake improves glycemic markers through reduction of fasting blood glucose, glycosylated hemoglobin, and HOMA-IR (homeostatic model assessment for insulin resistance) with lesser effects on insulin levels in the serum." (PMID 40725745, 2025). "During the insulin resistance condition, there is a dysregulation in the insulin response signaling pathway, the Protein Kinase B (Akt)/Phosphoinositide 3-kinase (PI3K)/Insulin receptor substrate 1 (IRS-1)." (PMID 41488874, 2025). "Here, we investigated the ability of lEVs and sEVs from insulin-resistant individuals to induce systemic, adipose tissue and liver insulin resistance in healthy mice." (PMID 39422717, 2025). "Effective metabolic control of type 2 diabetes is achieved through a combination treatment that decreases insulin resistance and enhances insulin secretion, thereby improving glucose tolerance." (PMID 40735430, 2025). "With respect to exercise interventions, intensities ≤4 MET significantly improved insulin resistance and insulin levels (both p < 0.01) and significantly affected HbA1c (p < 0.01) and FBS (p < 0.05)." (PMID 41346675, 2025). "HCV impairs insulin metabolism, leading to insulin resistance and hyperinsulinemia, which accelerate renal cell proliferation and tissue damage." (PMID 40564793, 2025). "Dysfunction of this pathway in insulin-sensitive organs contributes to systemic insulin resistance, metabolic dysregulation, and cellular apoptosis." (PMID 40564201, 2025). "The improvement in insulin resistance is reflected in the decrease of serum insulin levels and the reduction in body weight." (PMID 40386230, 2025). "Experimental work should explore how TyG-related insulin resistance promotes colorectal tumorigenesis through insulin/IGF-1 signaling, PI3K–AKT–mTOR activation, chronic inflammation, and microbiome or bile acid alterations." (PMID 41479778, 2025). "According to some studies, oral contraceptives containing estradiol tend to induce insulin resistance, whereas progestins enhance insulin secretion." (PMID 40391305, 2025). "As deficiencies in systemic glucose handling can be attributed to tissue‐specific insulin resistance, we tested for changes in insulin signaling in skeletal muscle (SKM) and liver." (PMID 40892707, 2025). "Insulin resistance is defined as at decrease in the sensitivity of targeted organs to circulating insulin." (PMID 39879508, 2025). "The insulin resistance (IR) related to glucose and insulin levels, is a key factor for metabolic syndrome, obesity, and cardiovascular diseases." (PMID 40727914, 2025). "Serum insulin level in mice at 20.5-month age was higher than mice at 2-month age, suggesting early-stage of insulin resistance in naturally aged mice." (PMID 39962087, 2025). ",21 (ii) Insulin resistance, which can suppress the insulin/IGF-1 signalling pathway, inhibit protein anabolism, and/or promote protein degradation, relates to the impairment of muscle strength." (PMID 40354753, 2025). "Both HGD and HBD diets induced a prediabetic state, demonstrated by altered fasting blood glucose, fructose, insulin levels, insulin resistance (HOMA-IR), and impaired OGTT." (PMID 40634535, 2025).